CD4 (CD4 molecule)
Diseases named in the same sentence as CD4 in open-access papers (continued):
Sharing a sentence is not in itself a finding about the gene and the disease.
Sepsis (continued). "Additionally, the relationship between the level of BTLA expression on circulating CD4+ T lymphocytes and the severity of sepsis has not been elucidated." (PMID 26329820, 2015). "In contrast, during sepsis, CD11clowCD45RB+ cells may not be beneficial because of their extraordinary ability to induce CD4 T cell apoptosis, which could promote immune suppression in the host, making the host more vulnerable to secondary infection." (PMID 26024301, 2015). "The severity of pin track sepsis was not influenced by HIV status (p = 0.9) or CD4 count (p = 0.2)." (PMID 25056512, 2014). "Patients with lower Treg cells did not have higher CD4+ T cells in severe sepsis." (PMID 23670410, 2013). "Although BTLA expression on CD4+ T cells and B cells has been well documented, and expression on these cells has been shown to contribute to a number of disease states, the significance of BTLA expression on lymphocytes during sepsis has yet to be fully addressed." (PMID 24289156, 2013). "Although we properly compared these ICU patients based on whether they were SIRS or septic, sampling at specific times following ICU admission and septic insult would provide more specific information about the timing of changes in BTLA expression on CD4+ T cells during SIRS and sepsis." (PMID 24289156, 2013). "Furthermore, we have demonstrated that the current sepsis classification (i.e., sepsis; severe sepsis; septic shock) does not accurately reflect the CD4+ lymphocyte ATP content, and arguably, the immune status of an individual patient." (PMID 20540723, 2010). "Furthermore, survivors of sepsis had a significantly higher CD4+ lymphocyte ATP content at the time of ICU admission than did nonsurvivors of sepsis (431 ± 41 ng/mL vs. 266 ± 53 ng/mL, respectively; P = 0.04)." (PMID 20540723, 2010). "Notably, the findings showed that the peripheral blood in patients with sepsis was infiltrated by higher proportions of monocytes, M0 macrophages, and neutrophils in the majority of datasets (≥4 datasets), but lower proportions of CD8 T cells, CD4 T cells, plasma, and resting natural killer cells." (PMID 40821971, 2025). "In addition, CD8 T cells but not CD4 T cells mediate bacterial clearance following sepsis." (PMID 38720893, 2024). "However, another studyverified that Gal-9 is not a ligand for TIM-3 on CD4+ T cells during sepsis." (PMID 38576606, 2024). "This indicates that T lymphocytes are incapable of maintaining IFN-gamma production 2-3 weeks after sepsis (similar to what has been previously reported), and that MDSCs at this time point may not be able to further suppress this aspect of CD4+ T lymphocyte function." (PMID 38720891, 2024). "Therefore, a sufficient amount of soluble CD4 protein can prevent excessive inflammatory activation of macrophages via alternation of MHC II-TLR signaling complex, that might benefit for a new paradigm of preventive treatment of sepsis." (PMID 37332010, 2023). "Notably, the main finding of this study is the increased expression of PD-1 and PDL-1 on CD4+ T cells in both sepsis groups, which was not correlated with clinical outcomes, while the increased expression of PDL-1 on CD8+ T cells was significant between deceased and surviving newborns." (PMID 36010061, 2022). "Thus, the low level CD3+CD4+CD69+T/CD3+CD8+CD69+T ratio in G- sepsis may display an adaptive immune state of excessive CD8+T activation and early occurrence of CD4+T suppression resulting from G- sepsis and correlate with the poor prognosis of G- sepsis." (PMID 36703970, 2022). "The prognostic role of low level CD3+CD4+CD69+T/CD3+CD8+CD69+T ratio in G- sepsis may be similar to that of low level CD4+T/CD8+T ratio in sepsis in previous studies, which may reflect the imbalance of T suppression/activation of adaptive immune response during pathophysiologic process in sepsis." (PMID 36703970, 2022). "However, the roles of IL-9-producing CD4(+) T cells and IL-9 in sepsis are not clear." (PMID 33941281, 2021).
Sepsis (continued). "Further, CD4 and CD8 T cell memory interaction is necessary to recapitulate findings in wild-type mice, indicating that involvement of these cells in the immune response independently could modulate human responses to sepsis and represent unique targets for future studies." (PMID 33329524, 2020). "However, the production of IFNγ by CD4+ and CD8+ T cells in whole splenocyte preparations from septic mice 2 days after CLP was strongly reduced upon in vitro stimulation with anti‐CD3 antibodies, reflecting the previously observed impaired cytokine production in sepsis." (PMID 26734459, 2015). "As previously observed in human and murine sepsis, this shift in the Treg/Teff ratio was probably due to the relative resistance of Tregs to apoptosis rather than to Treg expansion because the total number of CD4+Foxp3+ Tregs in the spleen was not significantly altered (data not shown)." (PMID 23724126, 2013). "While the expression of CD69 was upregulated during sepsis, the increased CD69+ naïve CD4+ T cell population has not been reported previously in this condition." (PMID 41208955, 2025). "Our study found a negative correlation between IL-7 and Th cells (CD4+) and Tc cells (CD8) on day 1 and day 5 in the sepsis survivors’ group." (PMID 40005375, 2025). "Compared with the sepsis + remazolam group, the contents of CD4+ and CD8+ T cells in the sepsis + saline were decreased, but there was no significant change between the sham operation + saline and sham operation + remazolam groups." (PMID 38646480, 2024). "When compared within the sepsis group or SAI group, CTLA-4 MFI on CD4+ lymphocytes from non-survivors was also significantly higher than that from survivors." (PMID 39104530, 2024). "Comparison of T lymphocyte subsets and markers on CD4+ T cells between patients with SAI and non-immunosuppressed sepsis patients." (PMID 39104530, 2024). "We found a statistically significant negative correlation between CD4+ and CD8+ T lymphocytes in both day 1 and day 5, suggesting a decrease in the value of both helper and cytotoxic lymphocytes, irrespective of sepsis or septic shock or the survival status." (PMID 39064603, 2024). "Compared with non-immunosuppressed patients with sepsis, patients with SAI had a higher 28-day mortality rate (37.5% vs 13.0%, P=0.039) and higher CTLA-4 mean fluorescence intensity (MFI) on CD4+ T cells (328.7 versus 78.7, P<0.0001)." (PMID 39104530, 2024). "In the cell-type RNA-Seq dataset, we found that CTLA4 was mainly expressed on CD4+ T cells but not CD8+ T cells, and CTLA4 was significantly up-regulated in sepsis." (PMID 37077915, 2023). "The better the patients recovered after treatment, the higher the levels of CD4+ and CD4+/CD8+, and the two were positively correlated, while CD3+ and CD8+ have no obvious correlation with the recovery of sepsis (Table-V)." (PMID 36694784, 2023). "B cells and CD4+ T cells decrease during the late phase of sepsis, meanwhile, CD8+ T cell levels do not change during sepsis." (PMID 38094297, 2023). "By blocking MDSC activity with nor-NOHA and l-NMMA, there was a significant decrease in CD4+FOXP3+ T cells (p = 0.014 and p = 0.045) in sepsis patients, but no such significant difference was observed in w/o sepsis patients and HCs." (PMID 35720398, 2022). "No patients in the study with Cryptococcus infection, CMV infection, sepsis, toxoplasmosis, or MAC infection had CD4 counts > 100 cells/mm3 (data not shown)." (PMID 35042469, 2022). "Consistent with CD4+ T cells, the percentage of T-bet+/CD8+ T cells in patients with sepsis was also higher than that in non-sepsis patients." (PMID 35898496, 2022). "The non-apoptotic CD4+ and CD8+ T cells in sepsis cases display inactivity or failure, with large phenotypic and functional impairments." (PMID 34335278, 2021).
Sepsis (continued). "The absence of IL-12 receptor expression in both CD4+ and CD8+ lymphocytes, which is consistent with existing human data suggests that immunity in elderly humans with sepsis is predominantly mediated by a Th-17 rather than a Th-1 response." (PMID 31658288, 2019). "RORγt expression by CD4+ T cells was less frequent in patients with sepsis (p<0.001), whereas T-bet expressing CD8+ T cells that do not express RORγt was lower in the sepsis patients." (PMID 31658288, 2019). "Furthermore as IL-23R expression was greater in CD3+ and CD3+CD4+ lymphocytes of patients with infection, who did not have multiple organ failure, then an exaggerated Th17 response in circulating lymphocytes does not appear to be the basis of sepsis induced organ failure." (PMID 31658288, 2019). "However, dose-dependent l-arginine supplementation in vitro increased CD4+ and CD8+ proliferation and enhanced secretion of T cell-related cytokines, such as IFNγ, suggesting that arginine supplementation at specific time points after sepsis may warrant further investigation." (PMID 31722736, 2019). "As expected, chronic T. gondii infection maintained a pool of CD4+ and CD8+ T cells (CD4+CD44+ and CD8+CD44+ T cells, respectively) independent of sepsis, thus confirming that such cells were activated by T. gondii." (PMID 28439500, 2017). "There is a serious lack of important immune cells such as CD4+ T-cells, CD8+ T-cells, B-cells, dendritic cells, and mononuclear cells in sepsis." (PMID 29259979, 2017). "In the memory CD4+ subset, there was no baseline difference in CD43 expression between sham animals, and 24h following sepsis induction the water-fed septic group demonstrated significantly increased CD43 expression." (PMID 27861506, 2016). "The in vitro proliferation of CD4+ and CD8+ T cells was very similar in all experimental settings and no sepsis‐dependent impairment was observed." (PMID 26734459, 2015). "The percentage CEACAM1 positive CD4+ T-cells in VLBW infants was not related to gestational age, antenatal steroids, and time of sampling after sepsis onset." (PMID 23894299, 2013). "On the other side, one research study has indicated that mHLA-DR, not CD4+, CD8+ or ratio of CD4+/CD8+, can predict the prognosis of severe sepsis." (PMID 23327199, 2013). "In those model systems, there is a much more prominent role for CD4+ T-cells, as opposed to PMNs or soluble CD28 as observed in the early phases of sepsis." (PMID 19672303, 2009). "CD4+ and CD8+ T-cells and CD19+ B-cells exhibited significantly raised portions of phosphatidylserine-positive populations in severe sepsis, but not in critically ill patients." (PMID 18925930, 2008). "Furthermore, the lack of lymphocyte subset analysis (CD4+/CD8+) represents a major biological limitation, preventing a more mechanistic understanding of how specific immune cell populations contribute to sepsis outcomes." (PMID 41398235, 2025). "Notably, CD4+ T cells, rather than CD8+ T cells, were significantly decreased in sepsis patients, indicating that CD4+ T cells play a critical role in adaptive immune suppression during sepsis." (PMID 41306770, 2025). "Importantly, we found that peripheral blood levels of miR-146b-5p were significantly lower in nonsurviving sepsis patients compared to HD, and these levels were positively correlated with CD3% and CD4%." (PMID 40642098, 2025). "Among 165 children with sepsis who completed lymphocyte subset analysis within 7 d of PICU admission in our study, the median absolute values of total T cells, CD4+ T cells, and CD8+ T cells in the non-survival group were significantly lower than those in the survival group." (PMID 39726536, 2024). "Moreover, there was a reduction of the non-effector subset, CD45RA + CD45RO- for both CD4 + and CD8 + that remained low even after sepsis resolution." (PMID 36279072, 2022).
Sepsis (continued). "In terms of cell function, IFN-γ expression in CD4+ T cells in patients with sepsis was higher than that in non-sepsis patients, but IFN-γ expression was lower in the severe sepsis group compared with the mild sepsis group." (PMID 35898496, 2022). "The benefit of CD4+ Tregs on the outcome after SIRS and sepsis is not fully understood." (PMID 36142962, 2022). "In order to assess whether EA at the three acupoints can regulate rat's immunity in sepsis, we detected the ratios of both CD3+CD4+ cells/CD3+CD8+ cells and Th17 cells/Treg cells in lymph node single-cell suspensions with flow cytometry." (PMID 33082818, 2020). "Thus, at the start of illness, both CD4+ and CD8+ T lymphocytes were activated in patients with infection, but not patients with sepsis." (PMID 31658288, 2019). "Expression levels of PD-1, PD-L1 and PD-L2 on four lymphocyte subsets (CD27 + CD19+ B cells, CD27-CD19+ B cells, CD27 + CD4+ T cells and CD27-CD4+ T cells) were compared between 22 patients with sepsis (including 11 survivors and 11 non-survivors) and 11 healthy controls using flow cytometry." (PMID 29661225, 2018). "By combining phenotypic analysis of exhaustion markers with functional analysis of cytokine production, we found that PD-1+ CD4+ cells in cancer hosts failed to make any cytokines following CLP, while the 2B4+ PD-1lo cells in cancer mice secreted increased TNF during sepsis." (PMID 29338031, 2018). "Moreover, the effect of sepsis on CXCR4 expression was T cell subset-specific, in that expression was not upregulated on CD8+ TCM, or on TEM in either the CD4+ or CD8+ compartments." (PMID 29232699, 2017). "In neither group was there a difference between water sepsis and alcohol sepsis in frequency of CD69 positivity, however, this dynamic change in the kinetics of expression suggests that alcohol delays the process of CD4+ T cell activation in sepsis." (PMID 27861506, 2016). "However, no additive effect was observed when T2DM and severe sepsis were combined, patients with severe sepsis combining T2DM had similar expression of PD-1+ CD4+ T cells and PD-1+ CD8+ T cells, and similar mortality rate as those with severe sepsis only." (PMID 27459386, 2016). "However, the CD4+ and CD8+ T-cell counts in non-survivors with severe sepsis after major surgery were approximately twice as high as those in survivors." (PMID 23670410, 2013). "For instance, the high expression of TXN in CD16+ monocytes may affect the progression of sepsis by regulating the release of pro-inflammatory cytokines or the ferroptosis pathway, while the absence of DPP4 expression in memory CD4+ T cells may exacerbate immune suppression." (PMID 40124361, 2025). "However, some studies have found that a single LPS injection did not increase PD-1 and TIM-3 expression in CD4+ T and CD8+ T cells in mice, whereas recurrent sepsis induced by multiple LPS stimulations resulted in a significant increase in PD-1 and TIM-3 expression." (PMID 38576606, 2024). "Therefore, we speculated that CHOP might not involved in regulating the population of CD4+ and CD8+ T cells in the development of CLP sepsis." (PMID 33159144, 2020). "However, recent studies suggested that regulatory T lymphocytes (Tregs), but not the ratio of CD4+/CD8+, could represent the immune function status of sepsis." (PMID 29859104, 2018). "Several studies have suggested that the CD4+CD25+Treg cells from septic mice are better suppressors of the proliferation of T effector cells, but the Ab-mediated depletion of Treg cells does not alter the sepsis-induced mortality in the cecal ligation and puncture (CLP) model." (PMID 23675534, 2013). "Several studies have suggested that the CD4+CD25+Treg cells from septic mice are better suppressors of the proliferation of T effector cells, but the Ab-mediated depletion of Treg cells does not affect the sepsis-induced mortality that is observed in the CLP model." (PMID 23675534, 2013).
Sepsis (continued). "In addition, level of immune suppression represented by CD4 cell count did not significantly affect the relationship between HIV-1 subtype and mortality in this cohort likely due to the overall low level of immune suppression among all sepsis cohort patients (median CD4 count <100 lymphocytes/mm3)." (PMID 23144755, 2012).
rheumatoid arthritis (644 papers, 1996 to 2026). A chronic, systemic autoimmune disorder characterized by inflammation in the synovial membranes and articular surfaces. "In patients with rheumatoid arthritis (RA), a highly differentiated CD4+ T cell population has been linked to increased disease activity, joint damage, and cardiovascular disease." (PMID 41235706, 2025). "Although CTLA4 is expressed on CD4+ T cells, the association of rheumatoid arthritis with the polygenic score for CD4+ T cell count was much weaker than the association with the GATE score for CTLA4." (PMID 39887658, 2025). "α/β-hydrolase domain-containing protein 11 (ABHD11) is a mitochondrial hydrolase, and its expression in CD4 + T-cells has been linked to remission status in rheumatoid arthritis." (PMID 41184294, 2025). "The occurrence and development of rheumatoid arthritis (RA) is mainly caused by Th17 cells being differentiated from CD4+ T cells." (PMID 40362651, 2025). "We addressed this by examining the associations of rheumatoid arthritis with polygenic scores for immune cell phenotypes; CD4+ T cells were the only cell type for which a polygenic score was positively associated with rheumatoid arthritis." (PMID 39887658, 2025). "Peripheral T helper (Tph) cells, a newly delineated subset of CD4+ T cells, have garnered attention for their pathogenic role in rheumatoid arthritis (RA)." (PMID 40144882, 2025). "Characteristic histopathological manifestations of rheumatoid arthritis‐associated tenosynovitis encompass synovial hyperplasia with leukocytic infiltration, predominantly CD4+ T lymphocytes and CD68+ macrophages." (PMID 41409891, 2025). "This rheumatoid arthritis GWAS signal colocalized with a TRAF1 eQTL signal in CD4+ T cells and increased risk for rheumatoid arthritis colocalized with increased expression of TRAF1." (PMID 38308274, 2024). "CD4+ T cells recognising citrullinated self-epitopes presented by HLA-DRB1 bearing the shared susceptibility epitope (SE) are implicated in rheumatoid arthritis (RA)." (PMID 39043656, 2024). "Evidence suggests that citrullinated GRP78 is an autoantigen associated with rheumatoid arthritis and type 1 diabetes, and CD4+ T cells that are reactive to GRP78 have been identified." (PMID 38672418, 2024). "CD4+ T cells recognising shared susceptibility epitope (SE) encoded HLA-DRB1 presenting citrullinated self-peptides are implicated in rheumatoid arthritis." (PMID 39043656, 2024). "An increase in CD4+ T cells in the synovium is closely linked to the pathogenesis of rheumatoid arthritis (RA)." (PMID 38640336, 2024). "For example, HLA-DRB1 seems to predispose to development of rheumatoid arthritis inducing the selection of autoreactive CD4 + T cells which can be intriguingly found in both synovial tissue and atherosclerotic plaque." (PMID 37219757, 2023). "Citrullinated GRP78 is an autoantigen in rheumatoid arthritis (RA) which is known to be associated with the HLA SE alleles as well as in type 1 diabetes and CD4 T cells reactive to citrullinated GRP78 have been identified." (PMID 36544781, 2022). "Hypermethylation of the TBCD gene in CD4+ T-cells is also associated with rheumatoid arthritis, an autoimmune disorder associated with stress exposure." (PMID 33789736, 2021). "This cell-type specific effect was corroborated by work in CD4+ cells using a rheumatoid arthritis model, which showed overexpression of Bcl-3 in these cells was implicated in the pathogenesis of rheumatoid arthritis." (PMID 31930327, 2020). "GoShifter confirmed a significant enrichment of rheumatoid arthritis variants in promoter regions specific to CD4+ memory T cells and also detected an enrichment of breast cancer variants in human mammary epithelial cells." (PMID 32477401, 2020). "While lupus-associated variants were enriched in genes specifically expressed in B cells, rheumatoid arthritis variants were enriched in genes specific to CD4+ memory T cells." (PMID 32477401, 2020).